RRAS (RAS related)
Description:
GTP-binding protein with GTPase activity, likely involved in the regulation of MAPK signaling pathway and thereby controlling multiple cellular processes. Regulates the organization of the actin cytoskeleton. With OSPBL3, modulates integrin beta-1 (ITGB1) activity.
Synonyms: R-Ras; RRAS1
Tractability: Small molecule: a structure with a bound ligand is known. Antibody: its Gene Ontology location is reachable by antibodies, with high confidence; UniProt places it where antibodies can reach, with medium confidence. PROTAC: ubiquitination databases record sites on it; its protein half-life has been measured.
Gene: Protein-coding gene on chromosome 19 (49,635,292 to 49,640,143, reverse strand). Ensembl gene ENSG00000126458.
Subcellular location: Cell membrane
Subcellular location (Human Protein Atlas): Vesicles
Pathways (Reactome):
Developmental Biology: SEMA3A-Plexin repulsion signaling by inhibiting Integrin adhesion; Sema4D mediated inhibition of cell attachment and migration
Gene Ontology:
Molecular function: GDP binding; GTPase activity; protein binding; protein-containing complex binding; G protein activity; GTP binding
Biological process: face morphogenesis; leukocyte differentiation; positive regulation of angiogenesis; positive regulation of endothelial cell migration; positive regulation of endothelial cell-matrix adhesion; positive regulation of vasculogenesis; regulation of ERK1 and ERK2 cascade; regulation of phosphatidylinositol 3-kinase/protein kinase B signal transduction; establishment or maintenance of cell polarity; Ras protein signal transduction; signal transduction
Cellular component: extracellular exosome; focal adhesion; plasma membrane; membrane
Genetic constraint (gnomAD): Loss-of-function variants: 14 observed, 18.63 expected, observed/expected ratio (o/e) 0.75, 90% interval 0.5 to 1.17. The upper end of that interval is the gene's LOEUF score, 1.17, which puts it in group 5 of 6, group 1 being the genes least tolerant of losing a copy. Missense variants: 279 observed, 271.29 expected, observed/expected ratio (o/e) 1.03, 90% interval 0.93 to 1.14. Synonymous variants: 130 observed, 114.14 expected, observed/expected ratio (o/e) 1.14, 90% interval 0.99 to 1.32.
Gene-disease validity (ClinGen):
ClinGen rates the evidence that RRAS causes each of these diseases.
Noonan syndrome (autosomal dominant): Limited. Noonan Syndrome (NS) is characterized by short stature, typical facial dysmorphism and congenital heart defects.
Homologues: Orthologues: chimpanzee RRAS (100% identical), macaque RRAS (99% identical), guinea pig RRAS (97% identical), pig RRAS (95% identical), mouse Rras (94% identical), rat Rras (93% identical), dog RRAS (74% identical), tropical clawed frog rras (62% identical), zebrafish rras (59% identical), Drosophila melanogaster Ras64B (53% identical), Caenorhabditis elegans ras-1 (51% identical). Paralogues in human: RRAS2 (61% identical), MRAS (48% identical), HRAS (47% identical), RIT1 (47% identical), NRAS (46% identical), KRAS (45% identical), RAP1B (44% identical), RAP1A (44% identical), RALB (42% identical), RALA (41% identical), RIT2 (41% identical), RAP2A (38% identical), and 23 more.
Diseases named in the same sentence as RRAS in open-access papers:
RRAS is named in the same sentence as 64 diseases in open-access papers, as found by Europe PMC text mining. Sharing a sentence is not in itself a finding about the gene and the disease. The quoted sentences say what the papers report.
glioma (7 papers, 2012 to 2024). A benign or malignant brain and spinal cord tumor that arises from glial cells (astrocytes, oligodendrocytes, ependymal cells). "In the unique module identified by DiME from the GBM glioma network, the RRAS oncogene, the SH3 domain binding kinase gene SBK1 and the transcription factor SOX8 involved in CNS development have the highest degrees of connectivity." (PMID 24523864, 2014).
melanoma (7 papers, 2009 to 2024). A malignant, usually aggressive tumor composed of atypical, neoplastic melanocytes. "ITGB1 and RRAS were highly expressed in all of the renal and most of the lung cancer cell lines, and both genes were expressed at relatively low or undetectable levels in all of the leukemia and most of the melanoma cell lines." (PMID 22570691, 2012). "RRAS binds FLNA (filamin A) (interaction 2), and this combination was required for migration of melanoma cells (see section below on FLNA)." (PMID 22570691, 2012).
breast carcinoma (6 papers, 2015 to 2024). "Recently, a negative association exists between activation of the RRAS gene and breast cancer progression, and loss of activation of this gene leads to carcinogenesis." (PMID 36452073, 2022). "The regulation of the expression of EGF and its downstream genes in the MAPK pathway, such as RRAS and MAPK3, have also been described as important inhibitors of apoptosis on breast cancer cells induced by chemotherapeutic agents." (PMID 30173296, 2018).
gastric cancer (5 papers, 2008 to 2023). A primary or metastatic malignant neoplasm involving the stomach. "The role of Ras-related associated with diabetes (RRAD) in gastric cancer (GC) or colorectal cancer (CRC) has not been investigated." (PMID 31857616, 2019).
RASopathies (5 papers, 2018 to 2024). "With the identification of RRAS as RASopathy-associated gene, that encodes a small GTPase controlling cell adhesion, spreading and migration, the question arose whether signaling routes other than RAF-MEK-ERK and PIK3-AKT may also be relevant in the pathogenesis of RASopathies." (PMID 29734338, 2018). "As expected, RAS proteins are the ones with the highest number of associations, although RASopathies related to SPRED1, MEK1/2, PTPN11, FGFR3 and SPRY1 may regulate RAS signaling differently, affecting primarily the classical RAS versus RRAS signaling." (PMID 34229750, 2021). "All three of these RAS proteins have been identified as mutated in RASopathies, along with non-canonical RAS proteins, RIT1, MRAS, RRAS, RRAS2 and RALA." (PMID 35103797, 2022).
glioblastoma (4 papers, 2009 to 2021). The most malignant astrocytic tumor (WHO grade IV). "RRAS regulates cell migration and has been identified as a glioblastoma multiforme signature gene." (PMID 24523864, 2014).
Noonan syndrome (4 papers, 2017 to 2024). "The RRAS p.Q87L variant, which has been previously shown to increase MAPK activity and inhibit apoptosis, has been reported in rapidly progressive JMML, and other germline variants in RRAS have been identified in Noonan Syndrome and JMML36." (PMID 29146900, 2017).
colon carcinoma (3 papers, 2009 to 2020). "Of note, ORP3 was shown to interact with R-Ras, a Ras-related cell signaling factor, which controls Ras signaling that is known to be one of the most often deregulated pathways in colon cancer." (PMID 32824360, 2020).
diabetes (2 papers, 2017 to 2019). "To further verify this result, we conducted western blot analysis and revealed that Ras-related associated with diabetes (RRAD) and Large tumor suppressor 2 (LATS2) protein levels was also increased in si-DUXAP10 transfected cells." (PMID 28029651, 2017).
Hypertension (2 papers, 2020 to 2023). The presence of chronic increased pressure in the systemic arterial system. "Another study aimed at finding rare and common variants associated with hypertension identified 31 novel genetic regions—rare missense variants in RBM47, COL21A1, and RRAS." (PMID 36902588, 2023). "They identified 30 new blood pressure- or hypertension-associated genetic regions in the general population, including 3 rare missense variants in RBM47, COL21A1 and RRAS with larger effects than common variants." (PMID 33240327, 2020).
bipolar disorder (1 paper, 2017). A disorder of the brain that causes unusual shifts in mood, energy, activity levels and the ability to carry out day-to-day tasks.
bladder cancer (1 paper, 2024). "METTL3 facilitates bladder cancer growth and metastasis by suppressing RRAS expression in a YTHDF2‐dependent manner." (PMID 38267969, 2024).
chronic lung disease (1 paper, 2025). According to the definitions of the American and British Thoracic Societies, including pulmonary functional tests, X-rays, and CT scans for items such as fibrosis, bronchiectasis, bullae, emphysema, nodular or lymphomatous abnormalities. "In summary, we have explored the crucial roles of angiogenesis and immunity in the onset and progression of ILD and COPD, and we identified COL10A1, EDN1, MMP1, and RRAS as potential novel therapeutic targets for chronic lung diseases." (PMID 40002743, 2025).
cognitive decline (1 paper, 2020). "cRAS activity is moderated by a downstream regulatory RAS pathway (rRAS), which is underactive in AD and is strongly associated with pathological hallmarks in human AD, and cognitive decline in animal models of CNS disease." (PMID 31982938, 2020).
germinoma (1 paper, 2016). A malignant germ cell tumor arising in the central nervous system. "We examined a total of 51 germinomas and 1 mixed GCT (germinoma and teratoma component) for mutations in KIT exons 11, 13, 17 and 18 as well as mutation hotspots in HRAS, KRAS, NRAS and RRAS-2." (PMID 27391150, 2016).
juvenile myelomonocytic leukemia (1 paper, 2021). A myelodysplastic/myeloproliferative neoplasm of childhood that is characterized by proliferation principally of the granulocytic and monocytic lineages. "Phenotypically related to pCMML, juvenile myelomonocytic leukemia (JMML) is a pediatric neoplasm often initiated by germline (CBL, NF1, PTPN11) or somatic (NRAS, KRAS, CBL, RRAS) RAS-activating mutations and is described as a bona fide RASopathy26,27." (PMID 34006870, 2021).
myelodysplastic syndrome (1 paper, 2022). A clonal hematopoietic disorder characterized by dysplasia and ineffective hematopoiesis in one or more of the hematopoietic cell lines. "Clinical studies point to the occurrence of pediatric myelodysplastic syndromes accompanied by germline RRAS mutations." (PMID 36968004, 2022).
nephritis (1 paper, 2008). Inflammation of renal tissue. "Increased levels of transcripts for pathway members including JAK3, STAT3, SOCS3, PTPN1, CDKN1A, RRAS and MAPK1 were observed in nephritis." (PMID 18980674, 2008).
tumor (29 papers, 2010 to 2024). "RAP1B is a ras-related-protein, and the tumor with amplification of RAP1B also had a point mutation affecting the amplified allele." (PMID 34272401, 2021). "In the case of tumor progression, mutations in several Ras related small GTPases leads to increased survival, proliferation, adhesion, and barrier permeability, favoring a metastatic phenotype." (PMID 24804765, 2014). "Meanwhile, YTHDF 2 recognizes the m6A site of RRAS and mediates the degradation of RRAS, promoting tumor growth and metastasis." (PMID 39289775, 2024). "We found that expression levels of PCSK9 and RRAS were significantly higher in normal tissue, and the rest 10 genes were overexpressed in tumor tissues." (PMID 36971680, 2023). "Only PCSK9 and RRAS were overexpressed in normal tissues, and the rest of ten genes were higher in tumor tissues." (PMID 36971680, 2023).
cancer (19 papers, 2010 to 2025). A tumor composed of atypical neoplastic, often pleomorphic cells that invade other tissues. "At least half of the top genes in both the correlating and anti-correlating categories are cancer-related, including oncogenes (RRAS and ALDOA), providing further insight into the observed inverse relationship between the two diseases." (PMID 28382934, 2017). "One of them, RalA, is a v-ral simian leukemia viral oncogene homolog A (ras-related) involved in tumorigenesis and cancer invasion." (PMID 22442671, 2012).
brain disease (1 paper, 2020). "Furthermore, five out of the 12 RG‐specific proteins (COL11A1, RRAS, GLUD1, IFITM3, and MGST1) are involved in human epileptic disorders prompting the hypothesis that modification of the extracellular environment is a common feature in this type of brain disease." (PMID 32378798, 2020).
metabolic disease (1 paper, 2018). A congenital disorder (due to inherited enzyme abnormality) or acquired (due to failure of a metabolically important organ) disorder resulting from an abnormal metabolic process. "Putative candidate genes FAM96B (family with sequence similarity 96 member B) and RRAD (Ras related glycolysis inhibitor and calcium channel regulator) for these SNPs are associated with gastrointestinal and metabolic diseases, and with the development of the digestive system and disorder networks." (PMID 30463512, 2018).
RRAS also shares sentences with these, for which no sentence is quoted: colorectal cancer (3 papers); adenocarcinoma (2); microphthalmia (2); Pancreatic Cancer (2); peripheral arterial disease (2); retinal diseases (2); retinopathies (2); bone marrow failure (1); breast tumours (1); cardio-facio-cutaneous syndrome (1); cervical cancer (1); cholangiocarcinoma (1); CNS tumors (1); Costello syndrome (1); cutaneous squamous cell carcinoma (1); diabetic angiopathy (1); diabetic retinopathy (1); endometrial cancer (1); endothelial dysfunction (1); experimental autoimmune encephalomyelitis (1); genetic disorder (1); hemangioma (1); hematologic malignancies (1); influenza (1); Insulin resistance (1); ischemia (1); kaposiform hemangioendothelioma (1); LEOPARD syndrome (1); leukemia (1); lung carcinoma (1).
A further 12 diseases each share a sentence with RRAS in 1 paper.